RN7SL4P (RNA, 7SL, cytoplasmic 4, pseudogene)
Synonyms: 7L28; RN7SL427P; RN7SLP1
Gene: Miscellaneous RNA gene on chromosome 3 (15,738,515 to 15,738,809, forward strand). Ensembl gene ENSG00000263740.
Homologues: Orthologues: chimpanzee Metazoa_SRP (87% identical), guinea pig Metazoa_SRP (78% identical), macaque Metazoa_SRP (78% identical). Paralogues in human: RN7SL2 (87% identical), RN7SL1 (86% identical), RN7SL3 (84% identical), RN7SL5P (83% identical), RN7SL480P (79% identical), RN7SL357P (79% identical), RN7SL444P (78% identical), RN7SL769P (78% identical), RN7SL230P (78% identical), RN7SL408P (78% identical), RN7SL45P (78% identical), RN7SL7P (78% identical), and 704 more.